DMP1 (dentin matrix acidic phosphoprotein 1)
Diseases named in the same sentence as DMP1 in open-access papers (continued):
Sharing a sentence is not in itself a finding about the gene and the disease.
cardiovascular disease (2 papers, 2013 to 2021). "We previously showed in Col4a3KO mice with CKD that overexpression of a bone matrix protein, DMP1, or treatment with ferric citrate, an iron-based phosphate binder, reduces FGF23 production and cardiovascular disease." (PMID 34334787, 2021).
genetic diseases (2 papers, 2015 to 2022). "This study extends the variant spectrum in PHEX and DMP1 and has shown the advantages of WES as an approach for the diagnosis of genetic diseases that are genetically heterogeneous." (PMID 36482408, 2022).
kidney disease (2 papers, 2015 to 2019). "The discrepancy between the two studies may be attributable to differences between species, to differences between osteocyte biology in the context of normal kidney function versus kidney disease, or to differences between the effects of vitamin D on DMP1 transcription and translation." (PMID 25774916, 2015).
brain disorder (1 paper, 2018). A disease affecting the brain or part of the brain. "We observed remarkable phenotypic shrinkage of astrocytes resulted from a lack of DMP1 glycosylation in cellular microenvironment, which was predictive of propensity for diverse diseases, including BBB disruption-mediated brain disorders." (PMID 28822114, 2018).
heart disease (1 paper, 2019). "Thus, our data support a potential therapeutic role for DMP1 in CKD to reduce FGF23 and potentially attenuate bone and heart disease." (PMID 31044094, 2019).
skeletal dysplasia (1 paper, 2010). Any Mendelian diseases that affects growth and development of the skeleton. "Herein we describe a family with ARHP owing to a novel homozygous DMP1 mutation and provide a detailed description of the associated skeletal dysplasia and carrier phenotype." (PMID 20499351, 2010).
DMP1 also shares sentences with these, for which no sentence is quoted: autosomal dominant hypophosphatemic rickets (12 papers); enthesopathies (3); X-linked hypophosphatemia (3); hereditary hypophosphatemic rickets (2); Hypercalciuria (2); left ventricular hypertrophy (2); acute myocardial infarction (1); ankylosis (1); aortic valve calcification (1); atherosclerosis (1); Autosomal Recessive Hypophosphatemic Rickets Type 2 (1); bacterial infection (1); Bladder Cancer (1); chondrodysplasia (1); Cognitive impairment (1); craniosynostosis (1); Creutzfeldt Jakob disease (1); Dental ankylosis (1); diabetic kidney disease (1); Dural ectasia (1); emphysema (1); enamel caries (1); endocrine disorder (1); gout (1); hereditary hypophosphatemic rickets with hypercalciuria (1); Hypertension (1); hypervitaminosis A (1); Hypocalcemia (1); hypoparathyroidism (1); Infertility (1).
A further 19 diseases each share a sentence with DMP1 in 1 paper.